PDE4DIP (phosphodiesterase 4D interacting protein)
Description:
Functions as an anchor sequestering components of the cAMP-dependent pathway to Golgi and/or centrosomes (By similarity). [Isoform 13]: Participates in microtubule dynamics, promoting microtubule assembly. Depending upon the cell context, may act at the level of the Golgi apparatus or that of the centrosome. In complex with AKAP9, recruits CAMSAP2 to the Golgi apparatus and tethers non-centrosomal minus-end microtubules to the Golgi, an important step for polarized cell movement. In complex with AKAP9, EB1/MAPRE1 and CDK5RAP2, contributes to microtubules nucleation and extension from the centrosome to the cell periphery, a crucial process for directed cell migration, mitotic spindle orientation and cell-cycle progression.
Synonyms: CMYA2; KIAA0454; KIAA0477; MMGL
Tractability: PROTAC: ubiquitination databases record sites on it; its protein half-life has been measured.
Gene: Protein-coding gene on chromosome 1 (148,808,140 to 149,048,286, forward strand). Ensembl gene ENSG00000178104.
Subcellular location: Golgi apparatus; Cytoplasm, cytoskeleton, microtubule organizing center, centrosome; Cytoplasm, cytoskeleton, microtubule organizing center, centrosome (Isoform 13); Cytoplasm, cytoskeleton
Subcellular location (Human Protein Atlas): Golgi apparatus
Gene Ontology:
Molecular function: molecular adaptor activity; protein binding; enzyme binding
Biological process: regulation of Golgi organization; centrosome cycle; protein-containing complex assembly
Cellular component: centrosome; cytoplasm; Golgi apparatus; nucleus; myofibril; cytoskeleton; microtubule organizing center
Genetic constraint (gnomAD): Loss-of-function variants: 26 observed, 46.69 expected, observed/expected ratio (o/e) 0.56, 90% interval 0.41 to 0.77. The upper end of that interval is the gene's LOEUF score, 0.77, which puts it in group 3 of 6, group 1 being the genes least tolerant of losing a copy. Missense variants: 485 observed, 631.97 expected, observed/expected ratio (o/e) 0.77, 90% interval 0.71 to 0.83. Synonymous variants: 194 observed, 239.04 expected, observed/expected ratio (o/e) 0.81, 90% interval 0.72 to 0.91.
Homologues: Orthologues: chimpanzee PDE4DIP (91% identical), dog PDE4DIP (82% identical), mouse Pde4dip (81% identical), rat Pde4dip (80% identical), pig PDE4DIP (79% identical), rabbit PDE4DIP (78% identical), tropical clawed frog pde4dip (42% identical), zebrafish pde4dip (31% identical). Paralogues in human: CDK5RAP2 (17% identical).
Diseases named in the same sentence as PDE4DIP in open-access papers:
PDE4DIP is named in the same sentence as 80 diseases in open-access papers, as found by Europe PMC text mining. Sharing a sentence is not in itself a finding about the gene and the disease. The quoted sentences say what the papers report.
breast carcinoma (7 papers, 2014 to 2023). "Known for its role in anchoring phosphodiesterase 4D to the Golgi/centrosome region of the cell, deleterious mutations of PDE4DIP have recently been demonstrated to be involved in breast cancer." (PMID 27829003, 2016). "The counterparts of these fusion proteins, such as MRPS30 and PDE4DIP, may also be associated with an increased risk for breast cancer and leptomeningeal disease progression, respectively." (PMID 31480474, 2019). "Phosphodiesterase 4D interacting protein (PDE4DIP) interacts with cAMP-specific phosphodiesterase 4D and its abnormal expression promotes the development of hematological malignancies, breast cancer, and pineal cell carcinoma." (PMID 37663233, 2023). "Also, an intronic SNP (rs2863344) in PDE4DIP has been associated with response to capecitabine 50, a common therapy for gastric and breast cancers, which indicates that expression and mutation status of this gene may be relevant to an informed treatment strategy for pancreatic cancer." (PMID 25594743, 2015). "However, there are relatively few reports on the PDE4DIP gene and tumor development, only including leukemia, breast cancer, and pineoblastoma." (PMID 37663233, 2023).
lung carcinoma (4 papers, 2020 to 2024). "Mutations in PDE4DIP have been previously identified predominantly during sequencing of tumor samples, e.g., in prostate, ovarian, or lung cancer, as well as in adult pineoblastoma." (PMID 34079577, 2021). "However, it still may be upregulated in thyroid and uterine cancer (PDE4DIP) and lung cancer (RAD17)." (PMID 38544823, 2024).
colorectal cancer (3 papers, 2020 to 2024). A primary or metastatic malignant neoplasm that affects the colon or rectum. "The missense variant, rs1664022, in PDE4DIP was identified in all the exomes analyzed in the present study, suggesting the possibility of utilizing it as a potential indicator for colorectal cancer." (PMID 38544823, 2024). "Here, we report for the first time the oncogenic role of PDE4DIP in colorectal cancer (CRC) growth and adaptive MEK inhibitor (MEKi) resistance." (PMID 37355626, 2023). "However, the role of PDE4DIP is poorly understood in the context of cancer, and further studies are required to validate the role of this particular SNP in PDE4DIP in colorectal cancer." (PMID 38544823, 2024). "PDE4DIP and RAD17 both do not play a major role in causing colorectal cancer, as observed and corroborated by gene expression profiling studies." (PMID 38544823, 2024).
dementia (3 papers, 2020 to 2025). Loss of intellectual abilities interfering with an individual's social and occupational functions. "A study using the SWIM algorithm to identify genes associated with dementia found that PDE4DIP is a key factor in the development of Alzheimer’s disease, vascular dementia, and frontotemporal dementia." (PMID 40149977, 2025). "Bioinformatic analyses indicated that elevated PDE4DIP expression co-occurs with dementia in the course of neurodegenerative diseases such as AD, vascular dementia, frontotemporal dementia, or major depressive disorder." (PMID 38534785, 2024). "Valproic acid was identified as a potential therapeutic agent that may regulate the mutual switch genes shared among the dementias (PDE4DIP, NEAT1, LPIN3, ADCYAP1, CCDC136, and ITPKB)." (PMID 32471155, 2020).
esophageal squamous cell carcinoma (3 papers, 2014 to 2020). Esophageal squamous cell carcinoma (ESCC) is a type of esophageal carcinoma (EC) that can affect any part of the esophagus, but is usually located in the upper or middle third. "The expression of serum PDE4DIP protein was linked to esophageal squamous cell carcinoma." (PMID 26062443, 2015). "PDE4DIP (also known as myomegalin, MMGL) is a tumor marker for diagnose and establish a prognosis in patients with esophageal squamous cell carcinoma." (PMID 25436889, 2014). "PDE4DIP (also known as myomegalin, MMGL) is a tumor marker for diagnosis and prognosis in patients with esophageal squamous cell carcinoma." (PMID 32784507, 2020).
glioblastoma (3 papers, 2018 to 2023). The most malignant astrocytic tumor (WHO grade IV). "Three of these Fyn-induced PKA interactors, AKAP9, PDE4DIP, and CDK5RAP2, were validated biochemically and were shown to exist in complex with Fyn and PKA in a glioblastoma cell line." (PMID 30274258, 2018).
leukemia (3 papers, 2020 to 2023). A malignant (clonal) hematologic disorder, involving hematopoietic stem cells and characterized by the presence of primitive or atypical myeloid or lymphoid cells in the bone marrow and the blood. "Our study first reported that PDE4DIP mutations in leukemia patients, suggesting PDE4DIP would be involved in pathogenesis of leukemia." (PMID 32638549, 2020). "Mutational analysis was used to map the genetic variants in leukemia, and found that the highest mutations occurred in PDE4DIP, followed by NOTCH2, FANCA, BCR, and ROS1 in almost all leukemia patients." (PMID 32638549, 2020). "These suggested that PDE4DIP might be a tumor suppressor gene in leukemia." (PMID 32638549, 2020).
asthma (2 papers, 2012 to 2015). "An additional nonsense mutation (c.C919T, p.R307X) in PDE4DIP was also associated with asthma risk in the African ancestry sample." (PMID 25591454, 2015). "Of these ten, variants in three genes (PDE4DIP, CBLB, and KALRN) were deemed of particular interest based on their functional prediction scores and previously reported function or asthma association." (PMID 23046476, 2012). "Three of these genes (PDE4DIP, CBLB, and KALRN) are of increased interest based on either their function or previous work in asthma." (PMID 23046476, 2012).
cardiac hypertrophy (2 papers, 2022). "Heterozygous Pde4dip-mutant mice had decreased ventricular inner dimensions (LVIDd and LVIDs) with increased fractional shortening but normal ECG, whereas homozygous LOF deletion of Pde4dip caused early lethality, attributed to ventricular hypertrophy." (PMID 39195995, 2022). "We therefore conclude that murine PDE4DIP is not required for cardiac hypertrophy, fibrosis or contractile dysfunction, at least in response to 12 weeks of hemodynamic challenges." (PMID 35860864, 2022).
endometrial cancer (2 papers, 2018 to 2023). Primary or metastatic malignant neoplasm involving the endometrium (mucous membrane that lines the endometrial cavity). "In this study, we further found that PDE4DIP had a higher frequency of mutations in some cancers, including endometrial cancer, bladder cancer, melanoma, NSCLC, hematological malignancies, and BRCA." (PMID 37663233, 2023). "Genetic variation analysis pointed out that the mutation frequency of PDE4DIP was higher in endometrial cancer, bladder cancer, melanoma, non-small cell lung cancer (NSCLC), hepatobiliary cancer, and BRCA, and the main types included mutation and amplification." (PMID 37663233, 2023).
hepatocellular carcinoma (2 papers, 2020 to 2025). A malignant tumor that arises from hepatocytes. "Additionally, genes like PDE4DIP, UBXN11, and AXIN1 are associated with hepatocellular carcinoma, and a de novo mutation in the SF3B2 gene relates to craniofacial microsomia." (PMID 40136557, 2025).
metastatic tumors (2 papers, 2021 to 2023). "PDE4DIP, ROBO1, and NOTCH4 mutations were observed only in metastatic tumors, whereas mutations specific to primary tumors were undetectable." (PMID 34158601, 2021). "Driver gene aberrations occurring exclusively in CSF cfDNA and not shared with primary/metastatic tumour or plasma cfDNA (where sequenced) were found in genes involved in histone modification (KAT6B, KMT2D, NUTM2A) and microtubule formation (PDE4DIP)." (PMID 37973922, 2023).
myeloproliferative disorder (2 papers, 2014 to 2015). A clonal hematopoietic stem cell disorder, characterized by proliferation in the bone marrow of one or more of the myeloid (i.e., granulocytic, erythroid, megakaryocytic, and mast cell) lineages. "PDE4DIP was reported to fuse to PDGRFB gene in myeloproliferative disorders." (PMID 26062443, 2015). "PDE4DIP is part of the PDGFR family and is known to mark eosinophilia and myeloproliferative disorders." (PMID 25506832, 2014).
pineoblastoma (2 papers, 2018 to 2021). Pineoblastoma is a rare, malignant type of supratentorial primitive neuroectodermal tumor (sPNET), found mainly in children (less than 10% of cases are reported in adults), and located in the pineal region of the brain but that can metastasize along the neuroaxis. "Expresion of PDE4DIP and DUF1220 proteins was present exclusively in pineoblastoma with PDE4DIP gain." (PMID 30030436, 2018).
schizophrenia (2 papers, 2021 to 2023). A major psychotic disorder characterized by abnormalities in the perception or expression of reality. "Others participate in neurodegenerative conditions; PD, schizophrenia, and intellectual disability (Tenm4, Pde4dip, Grid2, Arhgap18)." (PMID 36902345, 2023).
Stroke (2 papers, 2023). Sudden impairment of blood flow to a part of the brain due to occlusion or rupture of an artery to the brain. "Another GWAS significant protein-coding variant (rs1778155) in the PDE4DIP gene was associated with an increased risk of stroke and in our data PDE4DIP was up-regulated in participants with poor vs good outcome." (PMID 36691064, 2023). "Some studies have shown that there is a close association between PDE4DIP gene mutations and atrial fibrillation, stroke, and heart failure." (PMID 37663233, 2023). "PDE4DIP is an anchor protein, and its genetic mutations can result in impaired cell function, further leading to changes in intracellular targeting and cell survival, and the occurrence of diseases such as atrial fibrillation, stroke, and heart failure." (PMID 37663233, 2023).
acute myeloid leukemia (1 paper, 2023). Acute myeloid leukemia (AML) is a group of neoplasms arising from precursor cells committed to the myeloid cell-line differentiation. "In addition, because previous research has found that PDE4DIP is associated with hematological malignancies, we further explored the specific role of PDE4DIP in acute myeloid leukemia (LAML) in depth, providing a new target for the future diagnosis and treatment of various cancers, including LAML." (PMID 37663233, 2023). "We thoroughly analyzed the specific role of PDE4DIP in acute myeloid leukemia (LAML)." (PMID 37663233, 2023).
adrenocortical carcinomas (1 paper, 2020). "In addition, PDE4DIP variants are one of the most frequent in metastatic adrenocortical carcinomas in adults." (PMID 32098292, 2020).
Alstrom syndrome (1 paper, 2019). A multisystemic disorder characterized by cone-rod dystrophy, hearing loss, obesity, insulin resistance and hyperinsulinemia, type 2 diabetes mellitus, dilated cardiomyopathy (DCM), and progressive hepatic and renal dysfunction. "ALMS1 (Alstrom syndrome gene), ASPM (abnormal spindle-like microcephaly-associated protein), and PDE4DIP (phosphodiesterase 4D interacting protein) bind to microtubules and play a role in the formation of microtubule-based structures, including the centrosome and mitotic spindle." (PMID 31827074, 2019).
deafness (1 paper, 2023). An inherited or acquired condition characterized by the complete loss of the ability to hear from one or both ears. "Defects in the 30 shared genes are related to several pathologies, such as vision abnormalities (TMEM135), cancer (CDH6, FZD10, TIAM2), neuropsychiatric disorders (Tenm4, Pde4dip, Grid2), deafness (TFB1M), neutrophil disorders (VPS45) and others." (PMID 36902345, 2023).
dermatomyositis (1 paper, 2025). Dermatomyositis (DM) is a type of idiopathic inflammatory myopathy characterized by evocative skin lesions and symmetrical proximal muscle weakness. "In addition, genetic variations in several genes, including PDE4DIP and BRCA2, were commonly detected in cfDNA from dermatomyositis patients." (PMID 40599779, 2025).
glioma (1 paper, 2022). A benign or malignant brain and spinal cord tumor that arises from glial cells (astrocytes, oligodendrocytes, ependymal cells). "The role of PDE4DIP in GBM was previously reported: it has been demonstrated that this gene is down-regulated in glioma cell lines treated with dB-cAMP." (PMID 34996478, 2022).
intestinal cancer (1 paper, 2023). "PDE4DIP is commonly mutated in human cancers, and its alteration in mice leads to a predisposition to intestinal cancer." (PMID 37355626, 2023).
liver cancer (1 paper, 2022). An epithelial or non-epithelial malignant neoplasm that arises from the liver. "The mutation analysis was used to assess genetic variation of liver cancer, and it was found that PDE4DIP mutations were the highest in almost all patients with liver cancer, followed by SYNE1, KMT2C, PKHD1 and FN1." (PMID 35602894, 2022). "Our study suggests that PDE4DIP may be involved in the pathogenesis of liver cancer." (PMID 35602894, 2022).
mastocytosis (1 paper, 2020). A clonal myeloproliferative neoplasm characterized by the proliferation and accumulation of neoplastic mast cells in one or multiple organs or organ systems. "Four SNPs were more prevalent (in ABCA2, OTX2-AS1, HLA-V, and PDE4DIP genes) and 5 were less prevalent (in RPTN, CYP2B6, OR51Q1, FTCD, and rs9828758 near RP11 genes) in mastocytosis patients compared to a control cohort." (PMID 32752121, 2020).
medulloblastoma (1 paper, 2023). A malignant, invasive embryonal neoplasm arising from the cerebellum. "In medulloblastoma cells, PDE4DIP loss has been shown to mislocalize PDE4D3 from the centrosome, leading to local PKA overactivation." (PMID 37355626, 2023). "Moreover, two recent studies demonstrated that loss of Mmg (an alternatively spliced isoform of the PDE4DIP gene) suppresses the growth of medulloblastoma and that depletion of another specific isoform of PDE4DIP leads to inhibition of cell proliferation and motility." (PMID 37355626, 2023).
microcephaly (1 paper, 2020). A congenital or acquired developmental disorder in which the circumference of the head is smaller than normal for the person's age and sex. "PDE4DIP has been identified as a putative target for brain-enriched miRNA, where PDE4DIP is a homolog of CDK5RAP2, a gene that has been linked to microcephaly." (PMID 32787845, 2020).
papillary thyroid carcinoma (1 paper, 2021). "The variant PDE4DIP c.214C>T is described in the COSMIC database and was first observed in papillary thyroid carcinoma." (PMID 33503190, 2021).
paraganglioma (1 paper, 2023). A benign or malignant neoplasm arising from paraganglia located along the sympathetic or parasympathetic nerves. "The results indicated that there were differences in PDE4DIP expression in cancers, and in kidney chromophobe, LAML, pheochromocytoma and paraganglioma, thymoma, and uveal melanoma, PDE4DIP had potential prognostic value." (PMID 37663233, 2023).
squamous cell lung carcinoma (1 paper, 2022). A carcinoma arising from squamous bronchial epithelial cells. "Additionally, an exome-wide study of peripheral blood samples identified a frame-shift mutation in the PDE4DIP of cancer patients but not in cancer-free family members, suggesting a possible association of PDE4DIP with the development of squamous cell lung cancer." (PMID 36552904, 2022).
thymoma (1 paper, 2023). A neoplasm arising from the epithelial cells of the thymus. "The results of the Cox proportional hazards model showed that the expression of PDE4DIP was significantly correlated with lower OS in patients with LAML (p = 0.001), PCPG (p = 0.020), thymoma (THYM) (p = 0.002), and UVM (p = 0.003)." (PMID 37663233, 2023).